RNU6-75P (RNA, U6 small nuclear 75, pseudogene)
Synonyms: RNU6-75
Gene: Small nuclear RNA gene on chromosome 13 (90,781,766 to 90,781,869, reverse strand). Ensembl gene ENSG00000251753.
Homologues: Orthologues: chimpanzee U6 (93% identical), macaque U6 (82% identical), pig U6 (73% identical), pig U6 (67% identical). Paralogues in human: RNU6-1316P (79% identical), RNU6-1145P (78% identical), RNU6-1209P (78% identical), RNU6-742P (78% identical), RNU6-1075P (77% identical), RNU6-157P (77% identical), RNU6-393P (77% identical), RNU6-689P (77% identical), RNU6-1031P (76% identical), RNU6-151P (76% identical), RNU6-188P (76% identical), RNU6-29P (76% identical), and 1284 more.